LRRC1 (leucine rich repeat containing 1)
Diseases named in the same sentence as LRRC1 in open-access papers (continued):
Sharing a sentence is not in itself a finding about the gene and the disease.
cancer (7 papers, 2014 to 2025). A tumor composed of atypical neoplastic, often pleomorphic cells that invade other tissues. "Methylation of miR-124-3 contributes markedly to the downregulation of the gene, leading to the increased expression of its target gene, leucine-rich repeat-containing 1 (LRRC1), which is considered to be positively associated with cancer progression." (PMID 40227650, 2025). "It is known that LRRC1 is associated with cancer progression, and its 3′UTR contains two binding sites (GUGCCUUA) for miR-124-3 according to the miRDB database." (PMID 40227650, 2025). "Methylation of miR-124-3 contributes markedly to the downregulation of the gene, leading to the increased expression of its target gene, leucine-rich repeat-containing 1, which is considered to be positively associated with cancer progression." (PMID 40227650, 2025). "Differentially expressed genes between high and low LRRC1 expression were significantly enriched in pathways associated with cancer, amino acid metabolism, carbohydrate metabolism, and the immune system." (PMID 37505155, 2023). "This suggests that targeting LRRC1 through miRNA modulation could be an effective strategy across different cancer types." (PMID 40227650, 2025). "Furthermore, all of these genes, except LRRC1, were upregulated in most cancers, except the kidney chromophobe, in the TCGA pan-cancer cohort." (PMID 32213663, 2020). "From this subset, we prioritized five candidates (PSMA3, EWSR1, LRRC1, HNRNPD, and FAM98A) based on their SNR rankings, established roles in cancer pathways (e.g., proteasome function, RNA processing, and transcriptional regulation)." (PMID 41472850, 2025). "We detected the expression of the other six genes (MCM3, SPATS2, RRM2, NT5DC2, LRRC1, and RNASEH2A) in 30 pairs of HCC and para-carcinoma tissue by immunohistochemical staining assays." (PMID 32213663, 2020).
genetic disorders (1 paper, 2021). "LRRC1 (OMIM ∗608195) is not reported to be associated with any genetic disorders." (PMID 34177493, 2021).
LRRC1 also shares sentences with these, for which no sentence is quoted: Alzheimer disease (1 paper); frontotemporal dementia (1); Hepatitis (1); Oral Cancer (1); sarcoma (1); Stroke (1).